RORA (RAR related orphan receptor A)
Diseases named in the same sentence as RORA in open-access papers (continued):
Sharing a sentence is not in itself a finding about the gene and the disease.
primary Sjögren’s syndrome (2 papers, 2018 to 2025). "RORα expression in LSGs was determined in 46 patients with sicca syndrome who were referred to our department." (PMID 30189901, 2018). "However, the pathological significance of RORα in primary Sjögren’s syndrome (pSS) remains to be elucidated." (PMID 30189901, 2018). "RORα-expressing cells were observed in the LSGs of nearly all patients with sicca syndrome, even in those without obvious local lymphocytic sialadenitis (FS = 0)." (PMID 30189901, 2018).
psoriasis (2 papers, 2020 to 2024). An autoimmune condition characterized by red, well-delineated plaques with silvery scales that are usually on the extensor surfaces and scalp. "The findings suggest that XYAS may disrupt the vicious cycle between psoriasis and SDs by regulating the melatonin-RORα axis, protecting against mitochondrial damage and OS, and inhibiting pro-inflammatory cytokines secretion." (PMID 39411067, 2024). "Furthermore, the role of RORα in immune-mediated dermatological diseases and its involvement in the pathogenesis of psoriasis with SDs necessitates further exploration." (PMID 39411067, 2024). "The role of RORα in the pathogenesis of psoriasis has not been fully elucidated yet." (PMID 39411067, 2024).
rosacea (2 papers, 2021 to 2025). A chronic erythematous skin disorder that affects the face. "Based on the ol-DEGs, we revealed the TF regulatory network in AD/rosacea, indicating a central role of the 24 TFs in regulating the pathogenesis of AD and rosacea, including PPARG, STAT4, sox9, and RORA." (PMID 34899707, 2021). "In rosacea, proteomic and transcriptomic investigations have revealed enrichment of neurodegeneration-related proteins such as SNCA, GSK3B, and HSPA8, as well as regulatory hubs including PPARG, STAT4, and RORA, which converge on NF-κB, IL-17, and TNF signaling pathways." (PMID 41465136, 2025).
Stargardt disease (2 papers, 2023 to 2025). "In the context of Stargardt’s disease, RORA regulates inflammatory response pathways that include the proteins CD59." (PMID 40725253, 2025). "In mice lacking ABCA4, a rescue of Stargardt’s disease phenotype was observed in mice treated with AAV5 expressing human RORA (hRORA)." (PMID 40725253, 2025).
uveal melanoma (2 papers, 2019 to 2024). A melanoma derived from melanocytes of the uveal tract. "Our analysis on the correlation between RORα and RORγ and the presence of melanin in uveal melanoma, showed only a tendency for reverse correlation for RORα." (PMID 31235702, 2019). "RORα immunostaining of the cytoplasmic component in the uveal melanoma cells was found in 93.55% of cells." (PMID 31235702, 2019). "This is significant because until now there has been no paper published, that would describe presence of VDR, hydroxylases CYP27B1 and CYP24A1, and RORα and RORγ in the human uveal tract and uveal melanomas." (PMID 31235702, 2019). "In conclusion, we provide an evidence for the presence of the VDR, CYB27B1, CYP24A1, RORα and RORγ in uveal cells, which changes in uveal melanomas and suggest that these proteins are involved in clinical presentation and represent targets for novel therapeutic approaches." (PMID 31235702, 2019). "Moreover, cytoplasmic expression of VDR, RORα and RORγ (VDRc, RORαc and RORγc) was observed in the cells of uveal melanoma." (PMID 31235702, 2019). "Similar to RORα, the lowest level of nuclear RORγ was observed in the uveal melanoma cells." (PMID 31235702, 2019). "We examined the expression of melatonin receptors in uveal melanoma tumors from two separate cohorts and identified the presence of four receptors including the two main melatonin receptors MTNR1A and MTNR1B as well as RORα and NQO2." (PMID 39201396, 2024). "The current study also confirms the presence of RORα and NQO2 in uveal melanoma cells." (PMID 39201396, 2024). "The evaluation of RORα and melanin level in uveal melanoma did not reveal any significant correlations." (PMID 31235702, 2019). "To fill the gap in our knowledge on vitamin D activity in uveal melanoma, we decided to evaluate the expression pattern of the VDR, CYP27B1 and CYP24A1 hydroxylases and RORα and RORγ in the cells of uveal melanoma, in normal melanocytes and in other normal uveal cells in humans." (PMID 31235702, 2019).
adrenal hypoplasia (1 paper, 2015). "Included in this group were AR, Coup-TFα, Coup-TFβ, dosage-sensitive sex reversal-adrenal hypoplasia congenital critical region on the X chromosome, gene 1 (DAX1), ERα, ERRα, HNF4γ, liver receptor homolog-1 (LRH1), NOR1, NURR1, PPARγ, RARβ, RORα, RORβ, and VDR." (PMID 26244663, 2015).
aging (1 paper, 2017). A developmental process that is a deterioration and loss of function over time. "Our data showed associations between cognitive aging and single nucleotide polymorphisms (SNPs) in 4 key circadian clock genes, CLOCK rs3749473 (p = 0.0017), NPAS2 rs17655330 (p = 0.0013), RORA rs13329238 (p = 0.0009), and RORB rs10781247 (p = 7.9 × 10−5)." (PMID 28412756, 2017).
alopecia (1 paper, 2025). Hair loss usually from the scalp. "More research can be conducted on the regulatory effect of RORA on the autophagy levels of HFSCs, aiming to provide a theoretical basis for the molecular regulatory mechanisms of hair follicle development and offer new insights into research on the treatment of diseases such as alopecia." (PMID 40001602, 2025).
Arrhythmia (1 paper, 2025). Any cardiac rhythm other than the normal sinus rhythm. "Notably, the SAN_CM regulatory network also included the transcription factors BHLHE41 and RORA, regulators of the mammalian circadian clock, which were proposed to underlie time-of-day variation in arrhythmia susceptibility." (PMID 41162788, 2025).
arteriosclerosis (1 paper, 2020). A vascular disorder characterized by thickening and hardening of the walls of the arteries. "The results suggested that the control of NCEH1 expression by synthetic ligands of RORα might facilitate the development of novel anti-arteriosclerosis drugs." (PMID 32321446, 2020). "The RORα expression level and the malignancy of arteriosclerosis may be closely related." (PMID 32321446, 2020).
Arthritis (1 paper, 2019). Inflammation of a joint. "Overexpression of RORα reduced the clinical severity of arthritis and the extent of histological inflammation in a murine model of RA." (PMID 31636631, 2019).
atrial fibrillation (1 paper, 2025). A disorder characterized by an electrocardiographic finding of a supraventricular arrhythmia characterized by the replacement of consistent P waves by rapid oscillations or fibrillatory waves that vary in size, shape and timing and are accompanied by an irregular ventricular response. "In the atrial fibrillation dataset, LDHB, PFKFB2, CKAP4, CXCR4, DPEP2, and RORA genes showed an upregulation trend, while only the CD81 gene was downregulated in the disease group." (PMID 41359645, 2025). "In the selection of feature genes for atrial fibrillation, LDHB, DPEP2, BCL11B, CKAP4, RORA, PFKFB2, and CXCR4 were identified as potentially important predictors, with the model error being lowest when the number of genes reached eleven." (PMID 41359645, 2025).
bronchiolitis (1 paper, 2021). Inflammation of the bronchioles characterized by swelling of the bronchioles and mucus accumulation. "In summary, our study found that the specific transcription factors GATA-3, RORα and IL-17RB specifically expressed by the ILC2s in the bronchiolitis group had higher mRNA expression levels than the normal control group." (PMID 33514798, 2021). "Our study measured the levels of RORα and GATA-3 in the peripheral blood of patients with bronchiolitis." (PMID 33514798, 2021). "The results showed that the expression of transcription factors RORα and GATA-3 in the bronchiolitis group was higher than that in the normal control group (P < 0.05)." (PMID 33514798, 2021). "Based on RORα and GATA-3 as the specific markers of ILC2, it is suggested that ILC2s increase and activate in the peripheral blood of patients with bronchiolitis." (PMID 33514798, 2021).
Cirrhosis (1 paper, 2019). A chronic disorder of the liver in which liver tissue becomes scarred and is partially replaced by regenerative nodules and fibrotic tissue resulting in loss of liver function. "Analysis of the published database revealed higher RORα expression in cirrhosis samples than in normal samples, whereas the expression of other TFs was unchanged; therefore, we focused on further analysis of RORα." (PMID 31805036, 2019).
cleft lip (1 paper, 2024). Congenital defect in the upper lip where the maxillary prominence fails to merge with the merged medial nasal prominences. "The associations for the SNPs ABCA4 rs952499, SOX1-OT rs726455, and RORA rs877228 are of particular interest, as past research found associations between these genes and various craniofacial phenotypes, including cleft lip and/or palate." (PMID 38849772, 2024).
cognitive decline (1 paper, 2022).
cryptococcosis (1 paper, 2020). An acute or chronic, localized or disseminated infection by Cryptococcus neoformans. "Using mice lacking ILC2s due to conditional deletion of the transcription factor Rorα in immune cells, we provide direct evidence that ILC2s functionally contribute to mechanisms of immune polarization during cryptococcosis." (PMID 32117319, 2020).
cyst (1 paper, 2013). A sac-like closed membranous structure that may be empty or contain fluid or amorphous material. "Therefore, the in vivo cyst assays support the in vitro findings that RORα is required for normal keratinocyte differentiation, including the lipid layer formation program." (PMID 23922987, 2013).
delirium (1 paper, 2024). A disorder characterized by confusion; inattentiveness; disorientation; illusions; hallucinations; agitation; and in some instances autonomic nervous system overactivity. "Mechanistic studies revealed that TAN functioned as an RORα/γ agonist, leading to enhanced memory and cognition in LM-delirium mice." (PMID 38672774, 2024). "The authors suggest that TAN regulates the expression of RORα/γ-related genes such as E4bp4 and Bmal1, thereby promoting enhanced cognition in mice with LM-induced delirium, indicating the importance of TAN in preventing memory and cognitive deficits." (PMID 38672774, 2024).
disc degeneration (1 paper, 2024). "We have shown that there is an interaction between BMAL1 and RORα and they modulate HIF-1α activity as well as ECM homeostasis and perturbation in circadian clock genes results in disc degeneration." (PMID 38510179, 2024).
epidermal cyst (1 paper, 2013). "Gene silencing of RORα impaired the ability of keratinocytes to differentiate in an in vivo epidermal cyst model." (PMID 23922987, 2013).
esophageal cancer (1 paper, 2023). A primary or metastatic malignant neoplasm involving the esophagus. "In cervical and esophageal cancer, overexpression of PER2 suppressed cell proliferation and activation of REV-ERBα and RORα resulted in cancer cell death." (PMID 37968308, 2023).
food allergies (1 paper, 2024). "Second, four out of nine signature proteins downregulated in patients with AD and food allergies (i.e., Krt77, Asah1, Ggh, Cat) were significantly decreased in the RoraEKO epidermis vs. the control, indicating RORα could be critical for maintaining the expression levels of these important genes." (PMID 39409027, 2024).
hyperthyroidism (1 paper, 2010). Overactivity of the thyroid gland resulting in overproduction of thyroid hormone and increased metabolic rate. "Understanding the roles of RORα could therefore provide further information about the pleiotropic effects of late prenatal or early postnatal hypo- and hyperthyroidism in humans." (PMID 20663205, 2010).
Hypoglycemia (1 paper, 2022). A decreased concentration of glucose in the blood. "Thus, upregulation of RORα might play a critical role in the cytopathological process of hypoxia and hypoglycemia in ADSCs." (PMID 36425658, 2022).
Infertility (1 paper, 2021). "In C. elegans, NHR-23/NR1F1 (RORA) depletion causes infertility due to the arrest of primary spermatocytes rather than haploid sperm." (PMID 34557221, 2021).
insulinoma (1 paper, 2015). "For instance, overexpression of RORα in rat insulinoma cell lines increased expression and secretion of insulin." (PMID 26383638, 2015).
intestinal tumor (1 paper, 2022). "Deletion of RORα in adaptive T cells did not affect intestinal tumor burden, and exogenous IL-25 treatment in ILC2-replete and ILC2-deplete mice showed that ILC2s are essential for IL-25-mediated intestinal tumorigenesis." (PMID 35658010, 2022).
kidney cancer (1 paper, 2021). Primary or metastatic malignant neoplasm involving the kidney. "Five rhythmic genes, including PER2, DBP, PER3, CRY2, and RORA, have significant prognostic role in patient survival in at least two types of kidney cancer." (PMID 34977153, 2021).
lentivirus infection (1 paper, 2022). Virus diseases caused by the Lentivirus genus. "We also measured mRNA expression of these genes at the end of the treatment on day 6, and the results showed that lentivirus infection of either ERβ or RORA was successful." (PMID 35370982, 2022).
macular degeneration (1 paper, 2024). Loss of vision in the central portion of the retina (macula), secondary to retinal degeneration. "In summary, this study was performed to evaluate efficacy of RORA as a modifier gene therapy for macular degeneration." (PMID 38755404, 2024). "Here, we evaluated RORA as a potent, broad-spectrum modifier gene therapy for macular degeneration using the Abca4−/− mouse model." (PMID 38755404, 2024). "Two clinical trials are currently ongoing that evaluate the efficacy of RORA as a modifier gene therapy in different forms of macular degeneration, including dry AMD (NCT06018558) and STGD (NCT05956626)." (PMID 38755404, 2024). "RORA could be a broad-spectrum treatment for multiple forms of macular degeneration." (PMID 38755404, 2024).
mental disorder (1 paper, 2022). A disease that has its basis in the disruption of mental process. "Previous studies mainly focused on the association between the RORA gene and mental disorders, and the physiological function and physiopathological role of the rs2028122 genotypes remained unknown." (PMID 35769699, 2022).
metastatic tumours (1 paper, 2018). "We did not detect ILC2 cells in IL-33-deficient metastatic tumours (A9) established in either the mice transplanted with WT BM or RORα−/− BM." (PMID 29440650, 2018).
nematode infection (1 paper, 2023). "To further explore the relative roles of RORα cell-intrinsic expression in CD4 cells or ILC2 in the expulsion of worms after nematode infection, we used CreERT2 mice for tamoxifen-inducible Rora deficiency in CD4 cells (Rorafl/flCD4CreERT2) and ILC2s (Rorafl/flID2CreERT2)." (PMID 37387671, 2023).
nonalcoholic fatty liver (1 paper, 2024). "Further, an agonist of RORα attenuates nonalcoholic fatty liver progression in mice via upregulation of miR-122." (PMID 39684610, 2024).
oral cancer (1 paper, 2025). "The expression of RORα in oral cancer cells is down-regulated, while SR1078 can up-regulate and activate the expression of RORα, inhibit proliferation, migration, invasion, and metastasis, and induce apoptosis, suggesting that SR1078 may be a potential drug for the treatment of oral cancer." (PMID 41425709, 2025).
ovarian tumor (1 paper, 2020). "In this study, we analyzed the expression of RORα, RORγ, and VDR in ovarian tumor cells and identified an inverse correlation between their expression and a more aggressive phenotype and unfavorable clinical outcome." (PMID 33227893, 2020).
parasitic infection (1 paper, 2025). "However, it is probable that RORα deficiency is the principal cause for the lack of a proper Ilc2 response to the parasitic infection." (PMID 40559579, 2025).
paroxysmal AF (1 paper, 2021). "The expression of BMAL1, CRY2, NR1D2, PER2, and RORA was significantly lower in patients with persistent AF than in those with paroxysmal AF (persistent AF vs. paroxysmal AF, all p < 0.05)." (PMID 33430447, 2021).
placental abruption (1 paper, 2018). Vaginal bleeding preceding the 20th week of gestation. "Genetic variation in circadian rhythm genes ARNTL2, CRY2, DEC1, PER3 and RORA have also been associated with increased risk of placental abruption." (PMID 29768442, 2018).
Pontocerebellar atrophy (1 paper, 2024). Atrophy affecting the pons and the cerebellum. "In individuals with a heterozygous RORA loss of function, cerebellar hypoplasia and pontocerebellar atrophy are typically indicated." (PMID 39062725, 2024).
preeclampsia (1 paper, 2023). Preeclampsia is a hypertensive disorder of pregnancy that is characterized by new-onset hypertension with proteinuria presenting after 20 weeks of gestation, and depending on mild or severe forms may initially present with severe headache, visual disturbances, and hyperreflexia. "Moreover, increased expression of RAR-related orphan receptor A (RORA) has been observed in placenta of preeclampsia patients and HTR-8/SVneo cells." (PMID 38235138, 2023). "Mechanistically, RORA activates the JAK2/STAT3 signaling pathway to exacerbate preeclampsia." (PMID 38235138, 2023).
prostate tumour (1 paper, 2024). "Additionally, RORA gene expression was reduced in prostate tumour tissues, and in PCa cells compared to normal tissue or healthy prostate cells, a feature confirmed by other authors." (PMID 39010137, 2024).
renovascular hypertension (1 paper, 2023). High blood pressure secondary to renal artery stenosis. "RORα agonist prevented vulnerable plaque rupture and suppressed intraplaque hemorrhage in renovascular hypertension combined with low shear stress of hypercholesterolemic ApoE−/− mice." (PMID 36834872, 2023).
retinal degeneration (1 paper, 2024). Degeneration of the retina. "Rescue of retinal degeneration in Abca4−/− mice demonstrates the efficacy of RORA at resetting multiple disease pathways." (PMID 38755404, 2024).
retinoblastoma (1 paper, 2023). A malignant tumor that originates in the nuclear layer of the retina. "RA upregulates Rora expression in retinoblastoma cells, while putative ROR response elements (ROREs) have been identified on promoter regions of Rara and Rarb in human and rat, suggesting that RA and RORα enhance each other’s activity." (PMID 36672220, 2023).
sarcoidosis (1 paper, 2022). Sarcoidosis is a multisystemic disorder of unknown cause characterized by the formation of immune granulomas in involved organs. "In a prior gene co-expression analyses of peripheral blood and cutaneous lesions we noted that transcription factors, such as ETS1, IKZF3, LEF1, MYC, RORA, and SPI1 (PU.1), may be central players in aberrant processes associated with sarcoidosis." (PMID 36311769, 2022).
sarcopenia (1 paper, 2024). Progressive decline in muscle mass due to aging which results in decreased functional capacity of muscles. "Identification of fibre‐specific roles for RORα in different muscle fibre types will assist our understanding of the pathophysiology of muscle diseases, including myosteatosis and sarcopenia." (PMID 38272857, 2024).
Shock (1 paper, 2021). The state in which profound and widespread reduction of effective tissue perfusion leads first to reversible, and then if prolonged, to irreversible cellular injury. "Herein we show that in the absence of functional RORα in mice there is reduced susceptibility to LPS-induced endotoxic shock, with selective decreases in release of pro-inflammatory cytokines." (PMID 33767712, 2021).